RNU6-101P (RNA, U6 small nuclear 101, pseudogene)
Gene: Small nuclear RNA gene on chromosome 12 (101,765,406 to 101,765,509, reverse strand). Ensembl gene ENSG00000222255.
Homologues: Orthologues: chimpanzee U6 (100% identical), macaque U6 (92% identical), dog U6 (82% identical), pig U6 (79% identical), mouse Gm22557 (69% identical). Paralogues in human: RNU6-1042P (87% identical), RNU6-38P (87% identical), RNU6-1011P (85% identical), RNU6-1117P (85% identical), RNU6-1145P (85% identical), RNU6-47P (85% identical), RNU6-639P (85% identical), RNU6-891P (85% identical), RNU6-1331P (84% identical), RNU6-15P (84% identical), RNU6-409P (84% identical), RNU6-417P (84% identical), and 1287 more.